INS (insulin)
Diseases named in the same sentence as INS in open-access papers (continued):
Sharing a sentence is not in itself a finding about the gene and the disease.
atherosclerosis (continued). "Both imparted insulin sensitivity, reflecting by TyG, and excessive accumulation of visceral adiposity, indicated by WC and WHtR, were closely related to chronic inflammation, endothelium dysfunction and atherosclerosis, which all contributed to the development of ASCVD." (PMID 38898520, 2024). "Mice lacking CD36 have been reported to show increased insulin sensitivity, decreased inflammation in adipose tissue and resistant to the development of atherosclerosis." (PMID 39911578, 2024). "It prevents atherosclerosis by lowering total cholesterol, triglycerides, non-esterified fatty acids, and insulin levels in rat blood." (PMID 39203723, 2024). "Collectively, these data suggested that lipid (cholesterol)-driven and not glycemia- or insulin-related mechanisms appeared more likely to contribute to atherosclerosis in these mice." (PMID 36932214, 2023). "Ex vivo and preclinical data showed that DPP‐4is can restore the insulin‐induced vascular redox response and endothelial dysfunction, suggesting that the combination of a DPP‐4i and an insulin analogue might prevent atherosclerosis." (PMID 37528628, 2023). "PVAT dysfunction is induced by complex and not fully elucidated interactions among adipocyte hypoxia, insulin resistance, oxidative stress, vascular inflammation, and macrophage activation in the early stages of atherosclerosis." (PMID 37109222, 2023). "Network pharmacology analysis revealed that morusin, kuwanon C and morusyunnansin L are the main active compounds of MLF and that they amend insulin resistance and glycemia via the PI3K- Akt signaling pathway, lipid and atherosclerosis pathways, and the AGE-RAGE signaling pathway." (PMID 36278175, 2022). "Insulin resistance is associated with cardiovascular disease, but there are not enough data at present to show that increased insulin sensitivity reduces the progression of atherosclerosis." (PMID 36012362, 2022). "A more recently published study showed that exenatide treatment could prevent atherosclerosis progression in patients with T2DM, compared to insulin therapy." (PMID 32892547, 2021). "More importantly, since diabetic and cardiovascular patients were excluded from the study (see Section 4.2), it should be noted that the obese mice were insulin-resistant but not diabetic and that wild type mice do not develop atherosclerosis." (PMID 33916621, 2021). "A limitation is that the proteins included in the present proteomics assay were selected for their involvement in atherosclerosis and cardiovascular disease, rather than insulin resistance or other dimensions of metabolic disturbances." (PMID 34758886, 2021). "Besides its role in atherosclerosis, apoC-III has been proposed to induce the apoptosis of insulin-secreting pancreatic β-cells." (PMID 34440189, 2021). "Elevations of blood TC and non-HDL-C are a common phenomenon in the insulin-resistant and/or diabetic subjects, contributing to the development of atherosclerosis and cardiovascular diseases." (PMID 33322303, 2020). "As miR-941 is associated with metabolic processes, inflammation and cell proliferation through its role in insulin-activated, mitogen-activated protein kinase (MAPK)—and T-cell receptor signaling, a connection with atherosclerosis was suggested as a potential explanation." (PMID 33298968, 2020). "Altogether this indicates that DAPA treatment in vivo does not protect against atherosclerosis in Apoe−/−Irs2+/− mice and it seems to interfere with islet insulin secretion and adipose tissue insulin-signalling." (PMID 33287201, 2020). "Although HMW forms were described as the most active forms through its more beneficial activity on insulin sensitivity, inflammation and atherosclerosis, no prior study has evaluated the effect of hypoxemia on Ad a multimers." (PMID 30800074, 2019).
atherosclerosis (continued). "Moreover, mice treated with antisense oligonucleotides (ASOs) targeting ANGPTL3 messenger RNA (mRNA) manifested dose-dependent reductions in LDL cholesterol, TRG, atherosclerosis progression, and liver TRG content and an increase in insulin sensitivity." (PMID 30944669, 2019). "Thus, LPL and BMP7, which are associated with insulin and glucose homeostasis, and MCP2 and SST, which are associated with regulation of immune system processes and cell migration, may play important roles in both the formation and regression of atherosclerosis." (PMID 30958112, 2019). "Adding metformin to the insulin therapy and standard of care did not significantly affect atherosclerosis progression." (PMID 29020969, 2017). "Per os administration of colchicine did not influence atherosclerosis progression in cholesterol-fed rabbits, levels of IL-18, insulin and leptin." (PMID 28950870, 2017). "The gluten-free diet transiently altered GM composition in these mice, as compared to the gliadin-supplemented diet, but did not alter body weights, glucose tolerance, insulin levels, plasma lipids, or atherosclerosis." (PMID 26799618, 2016). "Here, NAMPT knockdown seemed to exert contradictory effects in these experiments, protecting against atherosclerosis without changing insulin sensitivity." (PMID 27229177, 2016). "It is likely, however, that CB2 is upregulated in the vasculature in pathologies such as atherosclerosis, where an anti-inflammatory role for CB2 activation has been identified, and we recently showed that high glucose or high insulin treatment increases the mRNA of CB2 in endothelial cells." (PMID 27633407, 2016). "Considering the findings in non-obese STZ-induced diabetic mice and the nature of this agent, it is reasonable to assume that lowering glucose levels can attenuate atherosclerosis independent of any insulin actions." (PMID 26606676, 2015). "The present study suggests that at elevated levels, leptin may favor atherosclerosis by promoting the synthesis of TNF-α and insulin." (PMID 25762868, 2015). "Zucker fatty rats are insulin resistant, hyperlipemic, and hyperinsulinemic but are not prone to develop atherosclerosis." (PMID 25785279, 2015). "The results will become available in the near future, and the findings might hold great clinical relevance to the prevention of atherosclerosis and subsequent CVD in patient with insulin-treated T2DM." (PMID 24607023, 2014). "In patients with initially proper metabolic control, the use of personal insulin pumps has a beneficial effect on the earliest stages of atherosclerosis in the assessment of IMT and FMD, even despite lack of significant improvement in HbA1c." (PMID 24347835, 2013). "The present findings extend these concepts to the gene network level, and delineates pathways related to NF-κB and TNF that are involved in inflammation and atherosclerosis, as well as focus genes related to ubiquitin, proteasome, histone, HNF4A, insulin and APP." (PMID 23874591, 2013). "Interestingly, the metabolic pathway, the insulin signaling pathway, the HIF-1 signaling pathway, the FoxO signaling pathway, and lipid and atherosclerosis pathways emerged as enriched pathways in both the network pharmacology and quantitative transcriptomics analyses." (PMID 40438591, 2025). "Insulin does not accelerate atherosclerosis and may decrease atherosclerosis by lowering glucose levels, although the protective effects are mainly observed in patients with type 1 DM over a protracted period." (PMID 38366387, 2024). "C-peptide plays different roles in T1DM, T2DM, or non-diabetic individuals, indicating that the regulation of atherosclerosis by C-peptide may be jointly influenced by blood glucose, insulin, and C-peptide concentrations." (PMID 37745697, 2023).
atherosclerosis (continued). "Atherosclerosis, or aging of the blood vessels, is a physiological process that has accelerated in the last decades by the overconsumption of carbohydrates as the primary sources of caloric intake, resulting in increased triglycerides and VLDL-cholesterol and insulin spikes." (PMID 37626767, 2023). "In the recent years, it was also found to regulate fat metabolism and related diseases through several pathways such as “Insulin resistance”, “Non-alcoholic fatty liver disease”, “AGE-RAGE signaling pathway in diabetic complications”, “Lipid and atherosclerosis” and “PI3K-Akt signaling pathway”." (PMID 35237299, 2022). "Conversely, strengths of the study include the use of a solid and validated ultrasound protocol for studying atherosclerosis and the availability of biochemical parameters of lipid and glycaemic metabolism not routinely measured (i.e., apo-B, lipid subfractions, insulin)." (PMID 35011818, 2021). "The relation of insulin and related factors with cardiovascular disease is increasingly studied, including for the insulin receptor substrate (IRS) and downstream molecules such as AKT as they relate to myocardial infarction and cardiac vessel pathologies such as atherosclerosis." (PMID 33858515, 2021). "The 6 ingredients were highly related to arteriosclerotic cardiovascular disease and atherosclerosis and could mainly interact with similar targets, e.g., GSK3B, PDPK1, PLAU, etc., or pathways, e.g., Insulin, VEGF, FoxO, etc, providing the basis for integrating plasma drug concentration." (PMID 32922299, 2020). "For the insulin resistance module of 32 genes, EnrichR enriched 136 KEGG pathways and further connected the top 15 pathways with 12 complementary pathways, including two new pathways—Fluid shear stress and atherosclerosis and EGFR tyrosine kinase inhibitor resistance." (PMID 32294959, 2020). "It is reasonable to speculate that the mechanisms relating atherosclerosis to the later onset of DM might be related to insulin resistance, rather than directly to a hyperglycaemic state." (PMID 31330868, 2019). "Furthermore, decreased insulin signalling in nonhaematopoietic cells, as achieved by transplantation of ApoE−/− mouse model of atherosclerosis with bone marrow cells from IRS1+/− IR+/− ApoE−/− mice, contributed to increased atherogenesis in these mice." (PMID 28899902, 2017). "Furthermore, decreased insulin signaling in non-hematopoietic cells, as achieved by transplantation of ApoE−/− mouse model of atherosclerosis with bone marrow cells from IRS1+/− IR+/− ApoE−/− mice, contributed to increased atherogenesis in these mice." (PMID 28752048, 2017). "An animal model to study the various pathways followed by MPs to promote atherosclerosis by augmenting endothelial dysfunction and upregulating release of proinflammatory mediators is high-fat diet (HFD) fed rats for prolonged period to make them obese and insulin resistant." (PMID 27066292, 2016). "This agent could be a useful tool to study the direct relationship between glycemia and atherosclerosis independent of insulin secretion and action in vivo." (PMID 26606676, 2015). "The stimulated synthesis of dermcidin due to the lack of systemic insulin might play an important role in the development of atherosclerosis in T1BDM." (PMID 24649391, 2014). "Therefore, reducing the stimulatory effect of insulin on VSMC proliferation and migration may provide new insights in the prevention of atherosclerosis." (PMID 24888351, 2014).
atherosclerosis (continued). "We have shown previously in nonhuman primates that soy protein containing isoflavones leads to improved body weight, insulin sensitivity, lipid profiles, and atherosclerosis compared to protein without soy isoflavones (casein), and does not increase the risk of cancer." (PMID 22046358, 2011). "In our study, IMT was measured as a surrogate endpoint to examine whether or not insulin therapy might promote atherosclerosis." (PMID 18507868, 2008). "In addition to the effect on atherosclerosis, elevated inflammatory cytokines (e.g., TNF-α) may stimulate skeletal muscle proteolysis and induce skeletal muscle insulin resistance by negatively regulating insulin signal transduction to glucose uptake." (PMID 39728272, 2024). "Given TRPM2’s role in both atherosclerosis and GLP-1-induced insulin secretion further research on GLP-1/TRPM2 interactions could enable further pharmacological targeting of macrophage-related inflammation in diabetes and ASCVD." (PMID 39200816, 2024). "In contrast, TNF, interferon regulatory factor 2 (IRF2) and interferon gamma (IFNG) were predicted to be inhibited and insulin activated in both datasets, and the computing of LARP1 activity was not possible in VAT samples from humans with atherosclerosis." (PMID 35737302, 2022). "While relative or absolute lack of insulin is the characteristics of T2DM, insulin is also involved in the development of atherosclerosis." (PMID 24489861, 2014). "At the end, our observations imply that measurement of serum insulin and calculation of the HOMA index even in nondiabetic individuals may have an added value to predict atherosclerosis over the next years." (PMID 27734010, 2015). "Although TRF improves insulin sensitivity, reduces inflammation, and extends lifespan in both sexes and across various ages, it is also important to note that, much like TRF, intermittent fasting has also been observed to have potentially negative effects on atherosclerosis and offspring metabolism." (PMID 40625849, 2025). "The results showed that intermittent fasting could not improve the 24 h blood glucose level and did not affect atherosclerosis, LDL-C, and HDL-C and significantly reduced insulin levels, improved insulin sensitivity and β-cell reactivity, and lowered blood pressure." (PMID 33376581, 2020).
breast cancer (743 papers, 1983 to 2026). A primary or metastatic malignant neoplasm involving the breast. "A meta-analysis of epidemiological studies also confirmed the increased risk of breast cancer associated with elevated insulin levels." (PMID 39940361, 2025). "Higher levels of fasting insulin are known to raise the risk of breast cancer recurrence and more significant overall mortality." (PMID 40783771, 2025). "Hitherto, prospective observational studies examining insulin levels and breast cancer incidence have shown direct associations." (PMID 39235717, 2025). "Multifactorial analysis showed that insulin (95% CI 1.812 [1.431–2.293], p < 0.001) was associated with progression-free survival in patients with breast cancer." (PMID 40860681, 2025). "Obesity is linked to elevated levels of various hormones, including insulin, which increases the risk of breast cancer and is associated with more aggressive cancer phenotypes." (PMID 39857438, 2025). "Our analysis confirms the benefits associated with PA in managing insulin and glucose levels across all participants, including breast cancer survivors." (PMID 40937951, 2025). "Prospective trials such as MA.32 have investigated its role in early-stage breast cancer, and secondary analyses suggest possible risk reduction in insulin-resistant populations." (PMID 41300964, 2025). "Increased insulin levels have mitogenic effects and are a significant risk factor for the development of breast cancer." (PMID 40678416, 2025). "A high BMI level is linked to increased levels of insulin and estrogen, both of which contribute to the development of breast cancer." (PMID 40989682, 2025). "Potential mechanisms for the protective effects of a healthier lifestyle, as indicated by a higher 2018 WCRF/AICR Score, on breast cancer risk include reduced inflammation, lower oxidative stress, favorable hormonal changes, and improved insulin sensitivity." (PMID 41261199, 2025). "Research findings are inconsistent with the formerly postulated reduced likelihood of breast cancer associated with taking metformin, or the higher risk associated with insulin utilization [RR 0.96; 95% CI (0.52–1.78)]." (PMID 40572709, 2025). "It is therefore crucial to elucidate the risk of breast cancer in women exposed to the increasingly common, insulin resistant state of GDM, as the existing evidence provides conflicting conclusions." (PMID 39497166, 2024). "It wasn’t until insulin was found to be associated with an increased risk of breast cancer that scholars began to focus on the potential bladder cancer risk of SGLT2 inhibitors." (PMID 39882521, 2024). "A recent Mendelian randomization study reported that genetically predicted fasting insulin and glucose levels were positively associated with breast cancer risk." (PMID 37096432, 2023). "Elevated insulin levels or resistance, as seen in conditions like obesity and type 2 diabetes, have been associated with an increased risk of breast cancer." (PMID 37575755, 2023). "Exercise is an effective self-management tool associated with body composition and reduced fasting insulin levels among breast cancer survivors." (PMID 36864418, 2023). "Anti-tumor activity against the human breast cancer cells, anti-endotoxin agent, surfactin for oral delivery of insulin, implicated in the bioaccumulation and biosorption of Pb and Ar." (PMID 37614639, 2023). "For example, TRF reduced the lung metastasis of obesity‐driven breast cancer in mice by increasing insulin sensitivity and restoring circadian rhythms, and nightly fasting for more than 13 h significantly decreased the risk of breast cancer recurrence." (PMID 36737846, 2023). "Recently, studies using a mediation analysis approach showed that fasting insulin plays a major role in explaining the adiposity–postmenopausal breast cancer association—attributing 58%–65.8% of the association to insulin pathways." (PMID 37096432, 2023).